INS (insulin)
Diseases named in the same sentence as INS in open-access papers (continued):
Sharing a sentence is not in itself a finding about the gene and the disease.
Insulin resistance (continued). "Amino acids – Studies of BCAAs, such as valine, leucine, and isoleucine supplementation in animals and humans, suggest that circulating amino acids may promote insulin resistance directly, possibly via disrupting insulin signaling in skeletal muscle." (PMID 34483960, 2021). "However, a post-hoc analysis suggested that intermittent fasting provided increased insulin sensitivity among patients with previous insulin resistance." (PMID 33444495, 2021). "This hypothesis suggests that dysregulated insulin delivery, which is present in T2D, could lead to dysregulation of hepatic lipid metabolism or selective insulin resistance through FoxO1, contributing to the accumulation of lipids." (PMID 33387681, 2021). "Although whether the level of cystatin C can accurately reflect insulin resistance remains to be verified, the role of insulin signaling pathway which was found in pathway-based association analyses cannot be ignored as the genetic background of cystatin C." (PMID 34899825, 2021). "Given the substantial changes in insulin therapy over time as a result of the DCCT with new analogs and continuous subcutaneous insulin infusion being used in children, the long-term impact on weight gain, insulin resistance, and cardiovascular health merits further study of intervention strategies." (PMID 33828529, 2021). "Also, in another cross-sectional study representative of the Spanish population ≥ 18 years, higher adherence to the SEAD was associated with lower levels of C-reactive protein, triglycerides, insulin, insulin resistance, and systolic blood pressure." (PMID 33557823, 2021). "Beside the determination of serum insulin, we calculated HOMA‐IR and ISI, and further concluded that feeding on MBBP‐bread for a long period could significantly increase insulin sensitivity and improve insulin resistance to help to alleviate T2D." (PMID 34026064, 2021). "However, the number of studied subjects was limited, all were morbidly obese, and the homeostasis model of insulin resistance (HOMA-IR) as a relatively rough estimate was used to evaluate the efficacy of insulin signaling." (PMID 34359991, 2021). "Combined exenatide and metformin showed better effects on female than male patients for improving insulin sensitivity and serum lipid profile, reducing insulin resistance, increasing adiponectin levels, and decreasing the levels of HbA1c, BMI, resistin, TNF-alpha, CRP (p<0.05)." (PMID 34367059, 2021). "Fasting insulin and the homeostatic model assessment of insulin resistance index (HOMA-IR) were significantly higher in the case group comparing to the control group, indicating the higher IR among the case group members (P = 0.041 and P = 0.027, respectively)." (PMID 33422126, 2021). "Indeed, the onset of overt T2D requires insufficient insulin secretion to compensate for insulin resistance." (PMID 33855202, 2021). "Importantly, mice fed a high-fat diet to induce insulin resistance showed impaired vascular insulin sensitivity: insulin signaling in endothelial cells was impaired, decreasing muscle perfusion." (PMID 34214082, 2021). "Thus, either supplying more exogenous insulin overcomes the potential insulin resistance or increasing insulin administration increases cognitive function." (PMID 34577866, 2021). "In women with GDM, however, there may be a baseline of chronic insulin resistance (decreased insulin-stimulated glucose disposal and decreased inhibition of lipolysis) present pre-pregnancy." (PMID 34073737, 2021). "HFD-fed mice developed insulin resistance, as evidenced by increased fasting glucose and insulin concentration, impaired glucose tolerance, decreased insulin responsiveness and an increase in the Homeostatic Model Assessment of Insulin Resistance (HOMA-IR)value, as compared to the control group." (PMID 33036203, 2020). "In response to insulin resistance, pancreatic β-cells increase insulin production." (PMID 32139775, 2020).
Insulin resistance (continued). "Therefore, high glucose induces insulin resistance that decreases glucose uptake in response to insulin." (PMID 32977673, 2020). "Insulin resistance is a consequence of impaired peripheral insulin signaling." (PMID 32512799, 2020). "Similarly, positive associations were observed for markers of insulin resistance (HOMA-IR, fasting insulin, reduced insulin sensitivity, increased leptin and reduced adiponectin) and systemic inflammation (c-reactive protein)." (PMID 32958048, 2020). "Importantly, in the presence of RSV, the HI-induced insulin resistance was prevented, and the insulin-stimulated glucose uptake and GLUT4 translocation was restored." (PMID 32230718, 2020). "Feeding with 60% Kcal HFD produces hyperinsulinemia and insulin resistance initially followed by treatment with STZ that causes the beta-cell destruction resulting normal to low levels of insulin concentration in non-genetic, outbred animals such as mice." (PMID 32987623, 2020). "In addition, PPARγ can affect insulin sensitivity by regulating adipocyte hormones, cytokines, and proteins that are involved in insulin resistance." (PMID 32047529, 2020). "This analysis showed that PA treatment was sufficient to induce brain insulin resistance with a reduction in insulin-induced Ser473 phosphorylation of AKT by 43%, while, unexpectedly, CHO + PA treatment did not result in a markedly decreased phosphorylation of AKT." (PMID 32456175, 2020). "In addition, high insulin levels drive obesity and further exacerbate insulin resistance, resulting in a vicious cycle." (PMID 32604970, 2020). "Thus, when insulin resistance increases, insulin secretion increases in compensation, meaning that both HOMA-R and β increase." (PMID 32053635, 2020). "However, it has also been documented that excess lipogenesis is associated with fatty liver and insulin resistance, and that decreasing the lipogenic pathway through SCD1 inhibition can restore insulin sensitivity." (PMID 32198362, 2020). "The focus of this review is to examine the effects of physical activity in aging on a class of lipid intermediates, ceramides, that have been implicated in obesity and inflammation-induced skeletal muscle insulin resistance and impair insulin signaling downstream of the receptor." (PMID 32098447, 2020). "MCP-1, a chemoattractant protein that recruits immune cells to sites of inflammation, and TNF-α, a pro-inflammatory cytokine that inhibits insulin secretion and induces apoptosis of β-cells, also play pivotal roles in the development of insulin resistance and hepatic steatosis." (PMID 32182914, 2020). "BCAAs are thought to modulate insulin secretion, and increased circulating BCAAs may promote insulin resistance by disrupting insulin signalling in skeletal muscle." (PMID 32500084, 2020). "Still, it is debatable which organ is the first target of insulin resistance, it seems likely that skeletal muscle may play a crucial role in this process (since it mediates over 70% of all insulin-mediated glucose disposal)." (PMID 32326243, 2020). "Although lnIS is considered a good index of insulin resistance and convenient to be obtained with clinical variables, it may not be sensitive enough to examine the effect of metformin on insulin sensitivity in this population." (PMID 33457425, 2020). "Our protocol of prolonged and repeated chronic stimulation with high insulin concentration is dissimilar from previous reports, its main purpose being to reproduce as closely as possible the hyperinsulinemia occurring in vivo which triggers insulin resistance." (PMID 32718202, 2020). "However, the pathogenesis mainly involves beta-cell dysfunction, reduced amount or sensitivity of insulin or insulin resistance (IR) along with oxidative stress, inflammation, mitochondrial dysfunction, and apoptosis." (PMID 32998300, 2020).
Insulin resistance (continued). "have found that HRT is associated with higher incidence of insulin resistance in women with TS compared with healthy age-matched women, whereas other studies have not shown significant effects on insulin sensitivity after 6 months." (PMID 33381083, 2020). "Adipose tissue-derived inflammation also promotes insulin resistance in glucose storage tissues that can lead to hyperinsulinemia, and insulin and insulin-like growth factors (IGF) such as IGF-1 have pro-mitogenic and anti-apoptotic effects that are cancer promotive." (PMID 33327948, 2020). "We also found a reduction in pancreatic islet mass, a large increase in insulin secretion, and signs of insulin resistance by reduced AKT phosphorylation in muscle and adipose tissue, which may be a risk factor for T2DM." (PMID 32283715, 2020). "The high insulin response in E4orf1-Tg mice may be due to relative insulin resistance resulted from higher body weight and % body fat in these mice." (PMID 32286259, 2020). "In podocytes, insulin activates IRS2 rather than IRS1.88Irs2‐depleted podocytes show insulin resistance, which is caused by upregulation of a protein called phosphatase and tensin homolog deleted on chromosome 10 (PTEN)." (PMID 31342643, 2020). "Thus, more dedifferentiated or immature adipocytes likely exist in white adipose tissues in individuals with insulin signalling dysfunction such as those with insulin resistance, although detailed work has to be done to confirm this issue." (PMID 31989870, 2020). "BCAA overload may cause insulin resistance by the activation of mTOR signaling, resulting in persistent IRS-1 phosphorylation by mTORC1 and inhibition of insulin signaling." (PMID 32178221, 2020). "During pregnancy, insulin resistance is gradually increased to ensure adequate carbohydrate supply for the growing fetus, and along with this, postprandial glucose levels, basal and stimulated insulin secretion, and hepatic glucose production are elevated." (PMID 32031649, 2020). "In agreement with the models of accelerated growth rate that related the catch-up fat phenotype with insulin resistance, our results point out that while the RDC diet caused insulin resistance measured as the blood insulin/glucose ratio, the SDC diet normalized this parameter." (PMID 32854204, 2020). "Restoration of insulin signalling is a therapeutic approach to reciprocate insulin resistance." (PMID 32210082, 2020). "However, support for the finding of in vivo insulin resistance during the HEC was provided by the finding of a significantly greater Glucose-Insulin Index value, an indicator of insulin resistance, for the AS160-KO versus WT rats." (PMID 32053588, 2020). "Therefore, any abnormality in the PI3K–AKT signaling pathway will affect insulin signal transduction, thereby promoting the occurrence and development of insulin resistance and type 2 diabetes." (PMID 32265717, 2020). "In the presence of insulin resistance, poor glycemic control reflects relative insulin insufficiency for the corresponding metabolic needs; insulin resistance and the shortage of insulin may promote a catabolic state." (PMID 32708504, 2020). "Insulin resistance and/or abnormal insulin secretion are the main characters of T2D." (PMID 33042976, 2020). "Gestational diabetes mellitus (GDM) is defined as glucose intolerance and increased insulin resistance which occurs most often during the second or third trimester of pregnancy while type 2 diabetes (T2D) is characterized by defects in insulin secretion and by impaired insulin sensitivity." (PMID 32626786, 2020). "We identify an interaction between the insulin-sensitivity modulating group of SNPs and pancreatic fat content, suggesting that variants determining insulin resistance are involved in flipping the action of pancreatic fat on insulin secretion to negative." (PMID 32725157, 2020).
Insulin resistance (continued). "The activated JNK acts on nuclear factor-κB (NF-κB) and activator protein-1 (AP-1) to produce more inflammatory factors, further reducing the sensitivity of insulin target cells toward insulin, finally forming a vicious circle and aggravating insulin resistance." (PMID 32942585, 2020). "Interestingly, selective deletion of hepatic ApoJ resulted in insulin resistance in the fasting state, as indicated by the fasting hyperglycemia, as well as failure to normalize glucose levels in the presence of elevated insulin levels." (PMID 32332780, 2020). "However, recent studies highlighted that the key molecular mechanism of dysmetabolism is not fat accumulation per se but the degree of hepatic fibrosis (excess liver fat content—lipotoxicity), leading to reduced insulin clearance, insulin resistance and T2D." (PMID 33102799, 2020). "For example, the change in insulin–to-carbohydrate ratio can be used to provide general information related to each pathogen on what to expect, such as the percentage of insulin resistance during the first days, in the middle, and at the final days of the infection." (PMID 32784178, 2020). "However, in obese subjects, elevated plasma insulin levels and insulin resistance can generate LPL dysfunction." (PMID 33322742, 2020). "Therefore, it is difficult to link the increased use of insulin in these two clusters to obesity related insulin resistance." (PMID 33167380, 2020). "Additionally, a reduction in insulin concentration and improvement of insulin resistance, analyzed by HOMA-IR, were observed in Tb-treated mice." (PMID 32882837, 2020). "Western blotting was used to detect whether inhibition of SIRT1 modulated the effect of MNAM on PA-induced insulin resistance via hepatocyte insulin signaling." (PMID 32280711, 2020). "Similarly, short sleep duration is also correlated with lower insulin sensitivity and increased insulin resistance, even after adjusting for adiposity." (PMID 32546151, 2020). "On the other hand, we found that insulin-resistant α7−/− mice exhibit an excessive inflammation in adipose tissue, which is probably in response to enhanced plasma NEFA levels, which are known factors causing inflammation and insulin resistance." (PMID 32708537, 2020). "Patients with liver cirrhosis—which may be engendered by a low liver mass and low extraction of insulin or shunting of circulating insulin from the portal system to systemic circulation—usually exhibit hyperinsulinemia and insulin resistance." (PMID 33315940, 2020). "Fat accumulation in the liver can cause insulin resistance but insulin resistance does not cause fat accumulation because insulin increases lipogenesis and fat esterification in the liver." (PMID 32183037, 2020). "Hypothetically, the adiposity-related insulin resistance might be more reversible than the defects in insulin secretion." (PMID 32712801, 2020). "Lower SHBG usually leads to more free and biologically active androgens in the circulation and might disrupt insulin secretion and pancreatic β-cell function and aggravate MetS and insulin resistance in women with PCOS." (PMID 33101409, 2020). "Other studies have further elaborated that reduced insulin‐stimulated muscle glycogen synthesis and glucose oxidation may drive chronic insulin resistance." (PMID 33038072, 2020). "Moreover, in MDC-CC, glycosylated hemoglobin (Hba1c) and fasting insulin levels were measured and insulin resistance was estimated using homeostatic model assessment (HOMA-IR)." (PMID 32751974, 2020). "The term metabolic inflammation is also increasingly used to explain emerging insulin resistance and links the observations that are made with regards to increasing levels of fasting insulin, decreasing adiponectin, elevated PAI-1 and CRP—all findings aligned with the elevated levels of endotoxin." (PMID 32151020, 2020). "Pesticides also induce insulin resistance by acting on insulin signaling pathways." (PMID 33371482, 2020).
Insulin resistance (continued). "miR-26a ameliorated insulin resistance and glucose tolerance, improved bone microarchitecture and quality, increased osteoblasts and bone formation, decreased osteoclasts, and promoted the insulin signaling pathway in diabetic mice." (PMID 32278305, 2020). "Moreover, liver-specific over-expression of human SREBP-1c (alb-SREBP-1c) mice had increased liver FA levels, serum TG and FFA, and insulin levels, indicating insulin resistance." (PMID 33324348, 2020). "Consequently, central obesity-related insulin resistance, as shown by elevated levels of plasma insulin and HbA1c, is likely to have contributed to the sex difference." (PMID 32306910, 2020). "Furthermore, the levels of plasma insulin and fasting blood glucose were used to examine insulin resistance." (PMID 33318479, 2020). "However, the failure of this event in response to insulin indicates an early stage of insulin resistance and T2D." (PMID 33038072, 2020). "Taking into consideration the repression of adipocyte ANGPTL4 mRNA by insulin, the upregulation of ANGPTL4 in insulin resistance may contribute to the postprandial dyslipidemia in insulin-resistant individuals via inhibition of LPL." (PMID 32504883, 2020). "Additionally, they show that simvastatin treatment induces higher plasma glucose levels in mice despite increased insulin plasma concentrations, consistent with insulin resistance." (PMID 32630698, 2020). "Plasma UAG and UAG/AG showed a negative correlation with HOMA-IR, while AG demonstrated a positive correlation, indicating that UAG might improve insulin sensitivity while AG induces insulin resistance." (PMID 32963741, 2020). "Finally, leptin can reduce the antioxidative and lipogenic effects of insulin, promoting insulin resistance." (PMID 32403968, 2020). "It should be noted that insulin resistance is dependent on fasting glucose and insulin levels." (PMID 31973038, 2020). "Some of the ceramides and sphingolipids in the cytosol are related to insulin resistance and some of the DAGs relate to better insulin sensitivity; some of the ceramides or DAGs in the nucleus are linked to either insulin resistance or better insulin sensitivity." (PMID 32903666, 2020). "Moreover, PHPT patients are at high risk for developing insulin resistance or T2D; PTX improves insulin sensitivity." (PMID 32751307, 2020). "Circulating pro-inflammatory cytokines may inhibit insulin signalling, promoting insulin resistance." (PMID 33086688, 2020). "The dill powder supplementation significantly decreased the mean serum levels of insulin, homeostatic model assessment of insulin resistance, low-density lipoprotein cholesterol, total cholesterol and malondialdehyde in the intervention group in comparison with the baseline measurements (P < 0.05)." (PMID 32503652, 2020). "Obesity is associated with higher insulin secretion that can occur irrespective of changes in insulin sensitivity, whereas impaired insulin clearance is associated with insulin resistance during obesity." (PMID 32860984, 2020). "The results observed here indicate that higher U-NM concentration is a risk for insulin resistance, but not for insulin secretion, when the concentrations are within the physiologic range." (PMID 32053635, 2020). "We have recently shown that feeding mice a HFD induces brain insulin resistance with a reduced mitochondrial stress response as early as three days of dietary exposure, while activation of brain insulin signaling counteracted these HFD-induced metabolic alterations." (PMID 32456175, 2020). "Furthermore, fasting improved metabolic parameters including glucose levels, insulin, and insulin resistance (HOMA-IR)." (PMID 33348700, 2020). "However, PLB2TAU mice displayed early signs of insulin resistance, i.e. higher blood glucose levels were detected 90 min post bolus injection of insulin, alongside an overall increase in total glucose excursion (p = 0.0178) compared with WT mice." (PMID 31396860, 2020).